BRD4 (bromodomain containing 4)
Diseases named in the same sentence as BRD4 in open-access papers (continued):
Sharing a sentence is not in itself a finding about the gene and the disease.
liver cancer (11 papers, 2016 to 2025). An epithelial or non-epithelial malignant neoplasm that arises from the liver. "Notably, BRD4 inhibition caused MYC-independent large-scale gene expression changes in liver cancer cells." (PMID 27081696, 2016). "Most significantly, the 8QAL protein can be targeted to suppress BRD4 function, which is important in hepatic cancer since BRD4 regulates cancer cell growth, proliferation, and survival." (PMID 41323392, 2025). "For verification, we first detected the expression of JMJD6 and BRD4 in liver cancer tissues and adjacent normal tissues by RT-qPCR." (PMID 37880710, 2023). "The correlation of the gene expression (PCAF, ISX, and BRD4) in liver cancer is also being investigated." (PMID 34173348, 2021). "Taken together, these data suggest that E2F2 identified by BRD4 inhibition is a novel target for control of cell cycle in liver cancer." (PMID 27081696, 2016). "Taken together, the results demonstrate that E2F2 is a direct target of the epigenetic reader BRD4 in liver cancer cells." (PMID 27081696, 2016). "Next, BRD4 expression was examined by Western blot analysis in five liver cancer cell lines (Hep3B, HepG2, Huh7, PLC/PFR/5 and SK-Hep1) along with the immortalized non-tumorigenic human hepatocyte cell line MIHA." (PMID 27081696, 2016). "Taken together, we found that over-expression of epigenetic reader BRD4 in liver cancer and for the first time demonstrate that the BET protein inhibitor suppresses E2F2 itself and its downstream cell cycle regulation circuit in liver cancer." (PMID 27081696, 2016). "Using serial expression microarray and loss of function experiments followed integrated mining, we revealed that E2F2 is the first-line target of BRD4 inhibition and a promising therapeutic target in liver cancer." (PMID 27081696, 2016). "Serial gene expression analyses with SK-Hep1 liver cancer cells treated with JQ1 to delineate the key player of BRD4 inhibition identified E2F2 as the first line of downstream direct target of BRD4." (PMID 27081696, 2016). "To obtain a comprehensive transcription landscape after BRD4 inhibition and its clinical significance in liver cancer, we separated JQ1 up- and down-regulated genes and investigated their expression pattern in a large cohort of patients." (PMID 27081696, 2016). "BRD4 was overexpressed in liver cancer cell lines and liver tumor tissue, compared to than normal in three large cohorts." (PMID 27081696, 2016). "Importantly, inhibition of p300, BRD4, CDK7 or MED1 reduces the expression of super-enhancer-associated oncogenes and exerts anticancer effects against liver cancer." (PMID 38135679, 2023). "The human liver cancer cell lines exhibited relatively high BRD4 expression, with the exception of HepG2 hepatoblastoma cell line, indicating that targeting BRD4 could be effective for liver cancer therapy." (PMID 27081696, 2016). "The collective results indicate that BRD4 could be a therapeutic target in liver cancer and its inhibition by small molecule has anti-tumor efficacy in liver cancer cell lines." (PMID 27081696, 2016). "In this study, we investigated whether epigenetic reader BRD4 inhibition has therapeutic efficacy in liver cancer." (PMID 27081696, 2016). "Meanwhile, short hairpin RNA (shRNA)-mediated knockdown of BRD2 and BRD4 in the liver cancer cell line Huh7 significantly slowed down cell proliferation, suggesting that both BRD2 and BRD4 were important for liver cancer cell growth." (PMID 39872506, 2024). "The super-enhancer “writer” p300, super-enhancer “reader” BRD4, and super-enhancer activity regulators CDK7 and MED1 are often over-expressed in human liver cancer tissues, and their over-expression predicts poor patient prognosis." (PMID 38135679, 2023). "BRD4 is significantly upregulated in HCC patients and in liver cancer cell lines, and the overexpression of BRD4 in cancer tissues is correlated with poor prognosis in HCC patients." (PMID 36726725, 2023).
liver cancer (continued). "Although the mRNA expression of ISX strongly correlates with those of BRD4 and PCAF in patients with HCC, denoting that they were co‐expressed in liver cancer cells, the interaction between ISX, BRD4, and PCAF remains to be at issue." (PMID 34173348, 2021). "The cutting points of ISX, BRD4, and PCAF separately were 2.0, 3.0, and 2.1 times of the mRNA expression in liver cancer tumors than that of the neighboring healthy tissues." (PMID 34173348, 2021). "BRD4 inhibition by JQ1 induced anti-tumorigenic effects including cell cycle arrest, reduced wound healing capacity and soft agar colony formation in liver cancer cell lines." (PMID 27081696, 2016). "We find that both BRD2 and BRD4 but not BRD3 are required for liver cancer cell growth, and even transient BET suppression using pan-BETis (JQ-1 and ABBV075) is sufficient to impede cell proliferation and xenograft tumor growth." (PMID 39872506, 2024). "BRD4 and JMJD6 were highly expressed in liver cancer tissues." (PMID 37880710, 2023). "BRD4 inhibition by JQ1 induced anti-tumorigenic effects including cell cycle arrest, cellular senescence, reduced wound healing capacity and soft agar colony formation in liver cancer cell lines." (PMID 27081696, 2016). "Applying the same principle, targeting the phase separation of BRD4 with the BRD4 degrader ARV-825, particularly focusing on its short isoform (BRD4S), known for forming distinct condensates in chromatin within liver cancer cells, has proven to be an efficacious approach for targeting HCC." (PMID 39777266, 2024). "Studies reveal a robust correlation between endogenous BRD4 puncta in the nuclei of liver cancer cell and BRD4S and total BRD4 levels, but not with the long isoform of BRD4L." (PMID 39777266, 2024). "BRD4 inhibition by JQ1 selectively repressed transcriptional networks induced by E2F2 not through MYC and inverts liver cancer related gene expression signature." (PMID 27081696, 2016).
Obesity (11 papers, 2017 to 2025). Accumulation of substantial excess body fat. "Although ATMs have been shown to be the major source of inflammatory mediators that are linked to obesity and insulin resistance, the possible pathological functions of macrophage Brd4 in metabolic diseases remain largely elusive." (PMID 33830083, 2021). "However, the role of Brd4 in obesity-associated inflammation and insulin resistance remains uncharacterized." (PMID 33830083, 2021). "Our study establishes Brd4 as an essential metabolic and transcriptional regulator of ATMs and indicates that Brd4 in ATMs could have been a potential therapeutic target for the prevention and treatment of obesity and the associated metabolic diseases." (PMID 33830083, 2021). "Evidence shows myeloid-specific deletion of Brd4 in mice protected from inflammation and diet-induced obesity." (PMID 40068774, 2025). "For example, the prevalence of Brd4 promotes obesity associated inflammation and overexpression of proinflammatory cytokines, such as interferons (IFNA4), are associated with obesity pathogenesis, which are both elevated only in the FED group." (PMID 38720938, 2023). "Meanwhile, BRD4 has been found to play roles in lipid accumulation related diseases like the obesity due to high-fat diet and fatty liver." (PMID 36309482, 2022). "In summary, our studies unravel a pathological role of Brd4 in diet-induced obesity and insulin resistance." (PMID 33830083, 2021). "A deficiency in Brd4, which is a BET family member and expressed primarily in white adipocytes, by gene targeting in mice was found to induce obesity." (PMID 34336926, 2021). "Myeloid lineage–specific Brd4 knockout (Brd4-CKO) mice were protected from diet-induced obesity with decreased respiratory exchange ratio but increased energy expenditure." (PMID 33830083, 2021). "Here, we demonstrated that myeloid lineage-specific Brd4 knockout (Brd4-CKO) mice were protected from high-fat diet–induced (HFD-induced) obesity with less fat accumulation, higher energy expenditure, and increased lipolysis in adipose tissue." (PMID 33830083, 2021). "To explore the potential role of Brd4-mediated innate immune response in obesity, we used a mouse model of obesity with HFD using WT (Brd4fl/fl) and Brd4-CKO (Brd4fl/fl-LysMCre) mice." (PMID 33830083, 2021). "The bromodomain and extra-terminal (BET) bromodomains, particularly BRD4, have been identified as promising therapeutic targets in the treatment of many human disorders such as cancer, inflammation, obesity, and cardiovascular disease." (PMID 30879350, 2019). "Indeed, several previous reports have shown that BRD4 modulates hepatic lipid metabolism and participates in fructose-inducible fatty liver and high-fat diet-induced obesity." (PMID 38977508, 2024). "The study had shown that Brd4 binds to the promoter and enhancer of GdF3 to promote PPARγ-dependent expression of GdF3 in macrophages and modulated lipid metabolism and diet-induced obesity." (PMID 36741233, 2023). "In addition, myeloid lineage-specific BRD4 knockout promotes lipolysis in adipose tissue and leads to reduced obesity in mice." (PMID 36015180, 2022). "Controlling the expression of Gdf3 in ATMs could be one of the mechanisms by which Brd4 modulates lipid metabolism and diet-induced obesity." (PMID 33830083, 2021). "This study suggests that Brd4 could be a potential therapeutic target for obesity and insulin resistance." (PMID 33830083, 2021). "Our study reveals, what we believe to be, a function of Brd4 in lipid metabolism and obesity, indicating that Brd4 could be a potential therapeutic target to prevent and treat obesity and the associated metabolic diseases." (PMID 33830083, 2021). "Specifically, Brd4 cooperates with PPARγ in ATMs to regulate the expression of Gdf3, which acts on the adipocytes to suppress the expression of lipases and lipolysis, resulting in fat accumulation and the development of obesity." (PMID 33830083, 2021).
Obesity (continued). "Brd4-CKO mice displayed improved insulin sensitivity in obesity." (PMID 33830083, 2021). "Therefore, Brd4 could be a target for the treatment of inflammatory metabolic diseases, including obesity." (PMID 33830083, 2021). "Overweight individuals (BMI ≥ 25) have higher Brd4 expression in blood samples than individuals with normal weight, and the expression levels of Brd4 positively correlate with the expression of Gdf3 in obese individuals, highlighting the importance of Brd4-Gdf3 regulatory pathway in obesity." (PMID 33830083, 2021). "Brd4 might cooperate with distinct transcription factors, such as NF-κB and PPARγ, to differentially regulate the expression of genes in ATMs to modulate the development of obesity and insulin resistance." (PMID 33830083, 2021). "Finally, we evaluated the relevance of Brd4 and Gdf3 to obesity in human patients." (PMID 33830083, 2021). "Because WAT is the key site mediating systemic inflammation during obesity, we evaluated the inflammation in WAT of WT and Brd4-CKO mice." (PMID 33830083, 2021). "Similar to Gdf3 knockout mice, Brd4-CKO mice had similar reduced fat accumulation and were resistance to HFD-induced obesity." (PMID 33830083, 2021). "It would be of great interest to investigate whether selective inhibition of Brd4 or macrophage Brd4 could affect Gdf3-ALK7 signaling pathway and also be an effective approach to treat obesity and insulin resistance." (PMID 33830083, 2021). "Therefore, regulating the balance between BRD4 and BRD2 activities may inhibit metabolic diseases, such as obesity, type 2 diabetes, and related complications." (PMID 34336926, 2021). "We identified a well-established obesity regulator of lipid metabolism, mir-33, as an important upstream regulator in the HFD group, and we highlighted for the first time a potentially important role for Brd4 in the regulation of genes altered by diet-induced obesity." (PMID 32927694, 2020). "Therefore, regulation of the balance between BRD4 and BRD2 activities may inhibit metabolic diseases, such as obesity, type 2 diabetes, and related complications." (PMID 28931940, 2017).
serous ovarian cancer (11 papers, 2018 to 2024). "Approximately 18% of the patients with high-grade serous ovarian carcinoma present somatic amplification of BRD4, which is often associated with increased BRD4 gene and protein expression." (PMID 34758842, 2021). "Another newly discovered subtype of HR proficient high-grade serous ovarian cancer has amplifications in the bromodomain and extraterminal 4 gene (BRD4) and is similarly associated with poor outcomes." (PMID 32044108, 2020). "We explored the prognostic role of the BRD4 gene and protein expression in advanced high-grade serous ovarian carcinoma (HGSC)." (PMID 38893083, 2024). "Using our collection of patient-derived xenografts (PDXs) representing high-grade serous ovarian cancer, we analyzed the correlation between the expression of BRD4 isoforms transcript vs. protein." (PMID 37705995, 2023). "The amplification of BRD4 in a significant subset of high-grade serous ovarian carcinomas (HGSC) has led to the development of BET inhibitors (BETi) as promising antitumour agents that have subsequently been evaluated in phase I/II clinical trials." (PMID 37060086, 2023). "In these studies we assessed the potential oncogenic activity of recurrent, focal BRD4 amplification in high-grade serous ovarian cancer (HGSOC)." (PMID 30036377, 2018). "In order to interrogate the transcriptional landscape of BRD4-amplified high-grade serous ovarian cancer (HGSOC) patients, we analyzed TCGA RNA-sequencing data." (PMID 30036377, 2018). "High expression of BRD4 promoted the progression of high-grade serous ovarian cancer." (PMID 32782441, 2020). "BRD4 amplification occurs most frequently (~18%) in high-grade serous ovarian cancer patients." (PMID 30036377, 2018). "We hypothesize that the presence of both BRD4 isoforms may be required for cooperative oncogenic activity in the context of high-grade serous ovarian cancer." (PMID 30036377, 2018). "The subsequent experiments were conducted with high-grade serous ovarian adenocarcinoma cell lines SKOV3 and OVCAR3 because of their high BRD4 expression levels." (PMID 38473320, 2024). "We here aim to explore the prognostic role of the BRD4 gene and protein expression in the ascitic fluid of patients with advanced FIGO III/IV high-grade serous ovarian carcinoma (HGSC)." (PMID 38893083, 2024). "A subset of High-grade Serous Ovarian Cancer (HGSOC) patients are typified by focal, recurrent BRD4 gene amplifications." (PMID 30036377, 2018). "First, we used existing ChIP-seq data in the well-vetted high-grade serous ovarian cancer cell line OVCAR3 to identify active enhancers by searching for co-localization of the histone modification histone H3 lysine 27 acetylation (H3K27ac) and BRD4 28–30." (PMID 35869079, 2022).
thyroid cancer (11 papers, 2017 to 2025). "In particular, BRD4 was identified to be over-expressed in PTC specimens when compared to normal tissues, pointing to the role of BRD4 in the development of thyroid cancer." (PMID 37111316, 2023). "Previous research studies have shown that BRD4 can promote the phenotype of thyroid cancer cells through the SHH pathway." (PMID 34956562, 2021). "Our results suggest that BRD4 protein degradation should be the main reason to explain ARV-825-induced superior anti-thyroid carcinoma cell activity." (PMID 32163373, 2020). "In TPC-1 cells and primary human thyroid carcinoma cells ARV-825 induced BRD4 protein degradation, causing downregulation of BRD4-dependent oncogenic proteins, including c-Myc, Bcl-xL and cyclin D1." (PMID 32163373, 2020). "Bromodomain-containing protein 4 (BRD4) is overexpressed in thyroid carcinoma, represents as an important therapeutic target." (PMID 32163373, 2020). "In the present study, ARV-825-induced anti-thyroid carcinoma cell activity was significantly more potent than the small molecule BRD4 inhibitors, including JQ1, CPI203, and GSK1210151A." (PMID 32163373, 2020). "It was significantly more potent in inhibiting thyroid carcinoma cells than the known small molecule BRD4 inhibitors." (PMID 32163373, 2020). "Results demonstrated that ARV-825 significantly inhibited cell viability (MTT OD), proliferation (EdU incorporation) and migration (“Transwell” assay) in BRD4-overexpressed primary thyroid carcinoma cells." (PMID 32163373, 2020). "Taken together, ARV-825 induces BRD4 protein degradation and inhibits thyroid carcinoma cell growth in vitro and in vivo." (PMID 32163373, 2020). "Our previous studies have demonstrated that BRD4 expression is significantly elevated in established and primary human thyroid carcinoma cells." (PMID 32163373, 2020). "Together, ARV-825 induced BRD4 protein degradation and downregulated its targeted genes in thyroid carcinoma cells." (PMID 32163373, 2020). "ARV-825 induced BRD4 protein degradation and downregulation of its targets, including c-Myc, Bcl-xL and cyclin D1 in thyroid carcinoma cells." (PMID 32163373, 2020). "In this study, we predicted and proved that BRD4 is a targeted gene of miR-141-3p by bioinformatics, and overexpression of BRD4 can partially reverse the inhibitory effect of miR-141-3p on the phenotype of thyroid cancer cells." (PMID 34956562, 2021). "It is speculated that miR-141-3p may inhibit the malignant behavior of thyroid cancer cells by regulating the abundance of BRD4." (PMID 34956562, 2021). "We have previously shown that BRD4 expression is elevated in thyroid carcinoma cells." (PMID 32163373, 2020). "Importantly, AZD5153, a novel and specific BRD4 inhibitor, potently inhibited thyroid carcinoma cell growth in vitro and in vivo." (PMID 32163373, 2020). "In thyroid carcinomas, MYC overexpression develops by various means, including MYC amplification or rearrangements, BRAFv600e mutation interactions, specific long noncoding RNA dysregulation, increased BRD4 protein production, and abnormal TERT expression, among others." (PMID 34997561, 2022). "Therefore, BRD4 degradation by its PROTAC compound ARV-825 could be novel therapeutic advance of thyroid carcinoma." (PMID 32163373, 2020). "Treatment of thyroid cancer cells with JQ1, which inhibits the acetyl-lysine recognition site of BRD4, enhances NIS expression and RAI uptake and apoptosis." (PMID 33995657, 2021). "BRD4 inhibition, by the small molecule inhibitor AZD5153, potently inhibited thyroid carcinoma cell growth in vitro and in vivo." (PMID 32163373, 2020). "Incidentally, by attaching to acetylated histones and subsequently influencing gene transcription, the epigenetic regulator bromodomain-containing protein 4 (BRD4) plays an essential role in the onset and progression of many illnesses, including thyroid cancer." (PMID 37111316, 2023).
thyroid cancer (continued). "In TPC-1 cells and “C1” primary thyroid carcinoma cells, ARV-825 was significantly more potent than the tested BRD4 inhibitors (at even higher concentrations) in inhibiting cell viability and proliferation (EdU incorporation) as well as inducing cell apoptosis (nuclear TUNEL staining)." (PMID 32163373, 2020). "Notably, BRD4 was found to be overexpressed in PTC samples compared with normal tissue, indicating that BRD4 may contribute to the progression of thyroid cancer." (PMID 40819127, 2025). "In addition, BRD4 methylation levels at the cg19287817 locus were found to be lower in cancer tissues than in normal tissues in BLCA, BRCA, cholangiocarcinoma, KIRC, KIRP, liver hepatocellular carcinoma, LUAD, LUSC, pheochromocytoma and paraganglioma, and thyroid carcinoma." (PMID 30988278, 2019).